MFN1 (mitofusin 1)
Diseases named in the same sentence as MFN1 in open-access papers (continued):
Sharing a sentence is not in itself a finding about the gene and the disease.
cardiomyopathy (14 papers, 2012 to 2025). A disease of the heart muscle or myocardium proper. "Experimental studies have demonstrated that the lethal cardiomyopathy observed in mice deficient in the fission protein Mff can be rescued by simultaneously deleting Mfn1." (PMID 38739929, 2024). "Cardiac ablation of both Mfn1 and Mfn2 causes a mild cardiomyopathy." (PMID 28190190, 2017). "Further, there is an abnormal increase in myocardial mitochondria, downregulation of mitochondrial biogenesis-related genes, and aggravation of cardiomyopathy after specific deletion of Mfn1 and Mfn2 in the mouse myocardium." (PMID 35097008, 2021). "PGC-1 knockdown in mice induces cardiomyopathy via fragmentation and elongation of cardiac mitochondria, which is related to changes in mitofusin 1 (MFN1), optic atrophy 1 (OPA1), and dynamin-related protein 1 (DRP1) expression." (PMID 35097008, 2021). "Combined ablation of both Mfn1 and Mfn2 in the adult murine heart induces a lethal cardiomyopathy after several weeks, probably due to the mitochondrial fragmentation present in these hearts." (PMID 28190190, 2017). "Additionally, nuclear genes like OPA1, Drp1, Mfn1, and Mfn2 regulate mitochondrial fusion and fission, and their altered expression disrupts mitochondrial morphology and dynamics, contributing to cardiomyopathy, arrhythmias, and overall cardiac dysfunction." (PMID 40416162, 2025). "But, there has been reported that overexpression of MFN1 or MFN2 rescues cardiomyopathy." (PMID 38156294, 2023). "Additionally, SGLT-2i can influence the mitochondrial fusion/fission proteins, such as Mitofusin-1 and Mitofusin-2, which may have potential in the treatment of cardiomyopathies and AF." (PMID 40004127, 2025). "Likewise, mice subjected to the triple knockout of Mfn1, Mfn2, and Drp1—resulting in simultaneous disruptions in both mitochondrial fission and fusion—exhibit enhanced viability, prolonged survival, and a delayed onset of cardiomyopathy." (PMID 38739929, 2024). "Clearly, Mfn1 and 2 have distinct roles: a single Mfn1 allele and no Mfn2 expression in mice did not affect baseline cardiac function, whereas mice with a single cardiac Mfn2 allele and no Mfn1 expression developed cardiomyopathy at 8 weeks of age." (PMID 25652199, 2015). "In adult cardiomyocytes, elimination of MFN1 and MFN2 induce mitochondrial dysfunction and fragmentation, leading to CH and cardiomyopathy." (PMID 36187489, 2022). "Not surprisingly, as Drp1 deficiency resulted in cardiomyopathy and mitochondrial morphology changes in cardiac-specific Drp1-KO, significant changes in mitochondrial morphology and abnormal cardiac remodeling were also observed in the hearts of Mfn1/2 DKO mice." (PMID 35822027, 2021). "For example, a cardiac-specific KO (cKO) of PGC-1α/β in postnatal mice caused mitochondrial fragmentation and altered expression of mitochondrial fusion (MFN1, OPA1) and fission (DRP1, FIS1) genes, and a decrease in mitochondrial respiration, finally culminating in lethality due to cardiomyopathy." (PMID 36187489, 2022). "Furthermore, cardiomyocyte expression of human Mfn1 or Mfn2 rescued the cardiomyopathy observed in Drosophila with no expression of mitochondrial assembly regulatory factor (MARF), a Drosophila ortholog of mammalian Mfns." (PMID 25652199, 2015).
Hyperglycemia (11 papers, 2018 to 2025). An increased concentration of glucose in the blood. "This morphological change is associated with decreased hemoglobin A1C levels and associated Mfn1 expression, suggesting that hyperglycemia promotes mitochondrial remodeling." (PMID 37895224, 2023). "Loss of Mfn1/2 in β-cells leads to severe hyperglycemia, reduced GSIS, and mtDNA depletion, which bears similarity to a previous report of selective Tfam deficiency in β-cells." (PMID 35487893, 2022). "Western blot analysis consistently revealed that sustained hyperglycemia resulted in reduced expression of mitofusin 1 (Mfn1), an indicator of mitochondrial fusion." (PMID 37928264, 2023). "In neonatal rat cardiomyocytes, hyperglycemia downregulates Opa1 and Mfn1 but upregulates Drp1 and Mfn2, affecting mitochondrial potential and increasing apoptosis." (PMID 37895224, 2023). "Hyperglycemia suppresses the expression of Opa1 and Mfn1 and promotes that of Drp1 and Mfn2 in neonatal rat cardiomyocytes, decreasing mitochondrial membrane potential and increasing apoptosis." (PMID 35665261, 2022). "Mfn1 expression is related to hemoglobin A1C, showing that hyperglycemia drives remodeling of the mitochondria." (PMID 35665261, 2022). "In contrast, both p-Drp-1637 and the fusion-related protein, Mfn-1, became reversely activated during hyperglycemia." (PMID 30002788, 2018). "In complementary studies, depletion of MFN1/2 found similar hyperglycemia, reductions in insulin secretion, and mitochondrial network fusion and respiration, however, these effects correlate more with effects on mitochondrial DNA (mtDNA) content rather than changes in fission/fusion." (PMID 38404962, 2024). "In the present study, the changes in MFN1 and FIS1 in our HFD+STZ animals are consistent with previous studies on hyperglycemia-induced mitochondrial fission and fragmentation." (PMID 36297069, 2022). "Studies have shown that hyperglycemia in T2DM patients was found to induce mitochondrial fission and reduce mitochondrial fusion, and decreased MFN1/2 reduced insulin receptor substrate-AKT (IRS-AKT) signaling and Glucose Transporter 4 (Glut4) translocation, further increasing insulin resistance." (PMID 41195385, 2025). "WB analysis showed that MFN1 levels were significantly decreased upon MIC26 deletion in both normoglycemia and hyperglycemia compared with respective WT cells which could account for increased fragmentation." (PMID 39393820, 2024).
pancreatic cancer (11 papers, 2018 to 2025). "Loss of STING or MFN1/2 has been shown to decrease the sensitivity of pancreatic cancer cells to ferroptosis in in vitro or xenograft mouse models." (PMID 40846966, 2025). "The findings of the subsequent study further demonstrated that STING activation triggers ferroptosis in human pancreatic cancer cell lines by enhancing MFN1/2-dependent mitochondrial fusion and mitophagy-mediated mitochondrial removal." (PMID 40846966, 2025). "STING or MFN1/2 knockout reduces the sensitivity of pancreatic cancer samples to ferroptosis in vitro xenograft mice." (PMID 40552295, 2025). "Specifically, they found that the ER protein STING1 (also known as STING or TMEM173) promoted ferroptosis in human pancreatic cancer cell lines by increasing mitochondrial fusion protein MFN1/2-dependent mitochondrial fusion." (PMID 37324946, 2023). "In contrast, deletion of the STING1 or MFN1/2 genes reduced the sensitivity of pancreatic cancer cells to ferroptosis." (PMID 37324946, 2023). "The ER protein TMEM173 was previously identified to enhance ferroptosis in human pancreatic cancer cell lines by enhancing MFN1/2-dependent mitochondrial fusion." (PMID 36359768, 2022). "Of note, one previous study have suggested that STING1 promotes ferroptosis through MFN1/2-dependent mitochondrial fusion in pancreatic cancer cells." (PMID 35697672, 2022). "STING promotes ferroptosis in pancreatic cancer by promoting MFN1/2-dependent mitochondrial fusion." (PMID 40552295, 2025). "In human pancreatic cancer cells, it has been observed that the endoplasmic reticulum protein stimulator of interferon genes (STING1) accumulates in mitochondria and interacts with the mitochondrial outer membrane protein mitofusins (MFN1/2)." (PMID 38155662, 2023). "Here, we show that the ER protein STING1 (also known as STING or TMEM173) promotes ferroptosis in human pancreatic cancer cell lines by increasing MFN1/2-dependent mitochondrial fusion, but not mitophagy-mediated mitochondrial removal." (PMID 34195205, 2021). "Consequently, in vitro or xenograft mouse models show that the genetic depletion of STING1 or MFN1/2 (but not the mitophagy regulator PINK1 or PRKN) reduces the sensitivity of pancreatic cancer cells to ferroptosis." (PMID 34195205, 2021).
Insulin resistance (10 papers, 2018 to 2025). Increased resistance towards insulin, that is, diminished effectiveness of insulin in reducing blood glucose levels. "Interestingly, the liver from Mfn1 knockout mice demonstrates a preference for using lipids as the main energy source and a more active complex I to protect against insulin resistance." (PMID 31551926, 2019). "Diabetic cardiomyopathy is marked by reduced expression of fusion proteins (Mfn1, Mfn2, OPA1), increased fission, and overproduction of reactive oxygen species (ROS), which contribute to insulin resistance and cardiac dysfunction." (PMID 41000071, 2025). "Protein expression for Mfn1 (P < 0.001), PGC1α (P < 0.05), BNIP3 (P < 0.0001), and mitochondrial complexes I‐V (P < 0.01) was also increased by RYGB, and Mfn1 expression negatively correlated with body weight, insulin resistance, and fasting plasma insulin." (PMID 29464885, 2018).
dilated cardiomyopathy (9 papers, 2015 to 2023). Cardiomyopathy which is characterized by dilation and contractile dysfunction of the left and right ventricles. "When Drp1 is ablated in the adult mouse heart causing hyper-fused mitochondria, the mice show dilated cardiomyopathy, while ablation of both Mfn1 and Mfn2 in the adult mouse heart causes a decrease in mitochondrial fusion leading to hypertrophy of the heart." (PMID 30102730, 2018). "Additionally, in mouse heart, hypertrophy or dilated cardiomyopathy result from either MFN1 or MFN2 deletion (which causes mitochondrial fragmentation) or DRP1 deletion (which causes hyperfused mitochondria)." (PMID 34608863, 2021). "Conditional knock out of Mfn1 and Mfn2 in adult hearts induced mitochondrial fragmentation, mitochondrial respiratory dysfunction, which lead to dilated cardiomyopathy." (PMID 33049718, 2020). "Studies have reported that MFN1/2 can act redundantly during fusion, and ablation of both results in mitochondrial structural abnormalities and dilated cardiomyopathy in the postnatal heart." (PMID 33425917, 2020). "Interestingly, mice with cardiac MFN1 deficiency maintained cardiac function and mitochondrial respiration, while cardiac MFN2 ablation resulted in dilated cardiomyopathy and hypertrophy." (PMID 37175915, 2023). "Nonetheless, in cardiac cells with dual MFN1 and MFN2 ablation, mitochondrial fragmentation, and rapidly lethal dilated cardiomyopathy was observed." (PMID 33425917, 2020). "Furthermore, conditional gene deletion of mitofusin 1 (MFN1) and MFN2 in adult hearts induces lethal dilated cardiomyopathy." (PMID 34070562, 2021).
viral infection (9 papers, 2010 to 2025). "Virus infection triggered the association of NLRP3 with Mfn1 and Mfn2 in LPS-primed BMDM in a ΔΨm-dependent fashion." (PMID 31540165, 2019). "To probe the effect of SARS-CoV-2 infection onthe mitochondrial proteins, we analyzed the levels of mitochondrialouter membrane proteins Mfn1 and Mfn2 in the mouse lung tissue withoutvirus infection and on 3 or 6 days after viral infection." (PMID 38386664, 2024). "The specific mechanisms contributed by MFN1/2 and the roles of these two MFNs in other viral infections remain to be further studied." (PMID 26717518, 2015). "We demonstrated that the redistribution of IPS-1 is induced by various viral infections and 5′ppp-RNA transfection and is dependent on a functional MFN1." (PMID 20661427, 2010). "On the one hand, this could indicate the role of Mfn1 as a modulator of the immune response to viral infections." (PMID 37515204, 2023). "They showed that the deletion-targeting of mitofusin 1 (Mfn1) and mitofusin 2 (Mfn2), two molecules involved in mitochondrial fusion, prevented cells from producing interferons and pro-inflammatory cytokines in response to viral infection." (PMID 31058096, 2019). "However, Mfn1 and Mfn2 have different effects in different virus infections." (PMID 40284870, 2025). "However, few reports explain the roles of Mfn1 and Mfn2 in viral infection." (PMID 40284870, 2025). "Of note, MFN1 may play an opposite role by interacting with MAVS during viral infection." (PMID 34482801, 2021). "Together, these data suggest that MFN1 and MFN2 interact with MAVS to fine-tune innate immune responses during viral infection." (PMID 34482801, 2021). "Our findings that MFN1 and MFN2 play distinct roles in DENV infection, RLR signaling for MFN1 and MMP maintaining for MFN2, support that these two similar proteins are not functionally redundant in viral infection." (PMID 26717518, 2015).
lung fibrosis (8 papers, 2019 to 2025). "We reveal that MFN1 or MFN2 deficiency abolishes the lipogenic metabolic response in AEC2 cells under bleomycin-induced mitochondrial damage and demonstrate that impaired regulation of lipid metabolism in the Mfn1/2iΔAEC2 mice drives lung fibrosis." (PMID 31358769, 2019). "Morphological and pathological assessment of lung sections from surviving (~17 weeks post tamoxifen treatment) Mfn1/2iΔAEC2 mice revealed significant increases in Masson trichrome positive staining for collagen deposition, indicative of lung fibrosis." (PMID 31358769, 2019). "Deletion of either Mfn1 or Mfn2 in murine AEC2 cells aggravated bleomycin-induced lung fibrosis, while deletion of both induced spontaneous lung fibrosis." (PMID 31358769, 2019). "In the bleomycin-induced lung fibrosis model, we found increased common genes which were regulated in both Mfn1−/− and Mfn2−/− AEC2 cells." (PMID 31358769, 2019). "Loss of MFN1, MFN2 or inhibiting lipid synthesis via fatty acid synthase deficiency in AEC2 cells exacerbates bleomycin-induced lung fibrosis." (PMID 31358769, 2019). "The knockdown of the mitochondrial fusion protein Mfn1/2 in lung AT-II cells increased the morbidity and mortality of pulmonary fibrosis in mice, because Mfn1/2 knockdown impaired lipid metabolism and synthesis and significantly decreased the number and area of the mitochondria." (PMID 40559960, 2025). "Single-gene deletion of Mfn1 or Mfn2 in AEC2 cells exacerbated bleomycin-induced lung fibrosis, but at baseline did not cause any obvious lung pathology." (PMID 31358769, 2019). "Moreover, combined AT2 deletion of both mitofusin 1 and 2 lead to spontaneous lung fibrosis." (PMID 32218238, 2020). "Collectively, the marked upregulation of purine metabolism in Mfn1/2−/− AEC2 cells and in bleomycin-treated Mfn1- or Mfn2-deficient AEC2 cells may play a direct role in promoting lung fibrosis, and the pathogenic role of AEC2-specific purine metabolism warrants future investigation." (PMID 31358769, 2019). "Importantly, deletion of Mfn1 or Mfn2 in murine AEC2 cells promotes experimental lung fibrosis and simultaneous deletion of Mfn1/2 in AEC2 cells not only impairs basal surfactant phospholipid and cholesterol metabolism but also leads to the development of spontaneous lung fibrosis." (PMID 31358769, 2019). "Mitofusin 1 and 2 are GTPases required for mitochondrial fusion, and AT2 deletion of either gene augmented lung fibrosis after bleomycin injury." (PMID 32218238, 2020). "Here we uncover a critical function for MFN1 and MFN2 in AEC2 lipid metabolism and development of lung fibrosis." (PMID 31358769, 2019). "The differential roles of MFN1 and MFN2 in AEC2 function regulation and lung fibrosis development require further exploration." (PMID 31358769, 2019). "Consistently, such distinct functions of MFN1 and MFN2 are highlighted by the observation that Mfn2iΔAEC2 mice develop more severe lung fibrosis than the Mfn1iΔAEC2 mice." (PMID 31358769, 2019). "MFN1 and MFN2 knockout aggravates bleomycin-induced pulmonary fibrosis in mice." (PMID 40559960, 2025). "In the bleomycin-induced lung fibrosis model, we did not observe that Mfn1−/− or Mfn2−/− AEC2 cells had significantly increased cell death 5 days after bleomycin administration." (PMID 31358769, 2019). "Additionally, deficiencies in the mitochondrial fusion proteins mitofusin 1 (MFN1) and mitofusin 2 (MFN2) can damage lipid metabolism in mouse AT2 cells, affecting surfactant lipid production and promoting the formation of spontaneous pulmonary fibrosis." (PMID 38625722, 2024). "Previous studies have indicated that the absence of mitochondrial fusion proteins mitofusin 1 (Mfn1) and mitofusin 2 (Mfn2) in murine AT2 cells results in spontaneous lung fibrosis." (PMID 39676102, 2024).
melanoma (8 papers, 2017 to 2025). A malignant, usually aggressive tumor composed of atypical, neoplastic melanocytes. "The raw RNA sequencing data of DNML1, MFN1, and OPA1 from normal and melanoma samples, associated with NRAS-type mutations, were analyzed from a previous study." (PMID 40141318, 2025). "To characterize the secretome of therapy-induced senescent melanoma cells, and understand the impact of Mfn1 silencing in protein secretion, we performed quantitative shotgun proteomics by LC–MS/MS." (PMID 38195762, 2024). "Here we expanded these observations evaluating the secretome of senescent melanoma cells using shotgun proteomics, and explored the impact of silencing Mfn1 on the SASP." (PMID 38195762, 2024). "We also assessed if Mfn1 silencing affected the expression of other cytokines and chemokines secreted by senescent melanoma cells." (PMID 38195762, 2024). "Similar to our data, a study conducted in senescent melanoma cells observed an increase in MFN1 and 2 expression and levels, indicating alterations in mitochondrial fusion." (PMID 39703460, 2024). "In a previous report we showed that senescence, induced by the DNA methylating agent temozolomide, increased the level of fusion proteins mitofusin 1 and 2 in melanoma, and silencing Mfn1 or Mfn2 expression reduced interleukin-6 secretion by senescent cells." (PMID 38195762, 2024). "We found that the levels of Mfn1 and Mfn2 and Opa1 protein were considerably reduced in cryptolepine treated melanoma cells." (PMID 28473727, 2017). "We then analyzed the impact of Mfn1 silencing on the extracellular proteome of non-senescent melanoma cells." (PMID 38195762, 2024). "Mfn1 silencing did not affect the sensitivity of melanoma cells to the drug, since similar half-maximal inhibitory concentrations (IC50) were found for cells transfected with shMfn1 (69 ± 4 μM) or shScr (66 ± 2 μM)." (PMID 38195762, 2024). "Here we study the impact of silencing Mfn1 on the secretome of senescent and non-senescent melanoma cells, using shotgun proteomics." (PMID 38195762, 2024). "We generated tumors with melanoma cells with and without mitofusin 1, by injecting shScr or shMfn1 cells subcutaneously in the hind leg of the mice." (PMID 38195762, 2024). "Mitofusin depletion was also protective in a different setting when tumors were generated with melanoma cells with or without Mfn1 silencing and senescence was induced in vivo by treatment with the methylating agent DTIC." (PMID 38195762, 2024). "Indeed transient knockdown of PTEN in PTENWT melanoma cells reduced MFN1 expression, thereby antagonizing WNT3A-mediated increased MFN1 expression and of note PTEN depletion appears to reduce MFN1 expression in these cells." (PMID 28092677, 2017). "Besides, Mfn1 silencing per se did not affect melanoma cell growth or migration in culture but had a significant effect in vivo reducing tumor volume." (PMID 38195762, 2024).